SVIL-AS1 (SVIL antisense RNA 1)
Synonyms: RP11-534G20.3
Gene: Transcribed unprocessed pseudogene on chromosome 10 (29,409,618 to 29,415,412, forward strand). Ensembl gene ENSG00000224597.
Diseases named in the same sentence as SVIL-AS1 in open-access papers:
SVIL-AS1 is named in the same sentence as 5 diseases in open-access papers, as found by Europe PMC text mining. Sharing a sentence is not in itself a finding about the gene and the disease. The quoted sentences say what the papers report.
breast carcinoma (1 paper, 2025). "Kaplan‐Meier analysis also demonstrated that high level of SVIL‐AS1 significantly correlated with reduced OS of breast cancer patients in TCGA dataset." (PMID 40135844, 2025). "Moreover, we analyzed SVIL‐AS1 expression in breast cancer subtypes and other cancer types." (PMID 40135844, 2025).
hepatocellular carcinoma (1 paper, 2025). A malignant tumor that arises from hepatocytes. "In TCGA dataset, overexpression of SVIL‐AS1 was observed in head and neck squamous carcinoma and hepatocellular carcinoma when compared to normal tissues." (PMID 40135844, 2025).
lung adenocarcinoma (1 paper, 2024). A carcinoma that arises from the lung and is characterized by the presence of malignant glandular epithelial cells. "LncRNA SVIL antisense RNA 1 (SVIL-AS1) was decreased in lung adenocarcinoma (LUAD) cells, abolished cell-cycle progression, and restrained cell proliferation." (PMID 39119602, 2024).
tumor (3 papers, 2020 to 2025). "Knockdown of SVIL‐AS1 also decreased the tumor growth of KU‐19‐19 xenografts." (PMID 40135844, 2025). "Tumour stage significantly associated with the expression of LINC00673 (p = 0.005), LINC01929 (p = 0.002), PCAT19 (p = 0.001), FENDRR (p = 8.33 × 10–6), SVIL-AS1 (p = 0.037), LANCL1-AS1 (p = 8.69 × 10–7), LINC00968 (p = 2.32 × 10–7) and ADAMTS9-AS2 (8.29 × 10–6) as determined by Kruskal–Wallis test." (PMID 32020063, 2020). "Recently, lncRNA SVIL antisense RNA 1 (SVIL-AS1), which was located on chromosome 10q13, has been found to be downregulated in LUAD and act as a tumor suppressor in LUAD tumorigenesis in a E2F1-dependent manner." (PMID 37069649, 2023).
cancer (1 paper, 2025). A tumor composed of atypical neoplastic, often pleomorphic cells that invade other tissues. "We found that SVIL‐AS1 could enhance the proliferation of cancer cells with AKT1E17K mutation by interacting with PPP2R2A and preventing AKT1 dephosphorylation." (PMID 40135844, 2025). "Furthermore, we show that targeting SVIL‐AS1 can sensitize AKT1E17K cancer cells to AKT1 allosteric inhibitor and the PI3Kα inhibitor." (PMID 40135844, 2025).